MACC1 (MET transcriptional regulator MACC1)
Diseases named in the same sentence as MACC1 in open-access papers (continued):
Sharing a sentence is not in itself a finding about the gene and the disease.
cancer (continued). "We were able to demonstrate that circulating transcripts of MACC1 and S100A4 are detectable in blood of cancer patients and serve as reliable biomarkers for OS and MFS." (PMID 36008464, 2022). "Taken together, our results show a KO-specific role of CC genes in regulating cancer phenotype and affecting both EMT gene expression and correlation patterns, and highlight MACC1 as being strongly impacted, especially via ARNTL KO." (PMID 35884519, 2022). "In GC, under-expressed miR-944 upregulates MACC1 expression and activates the PI3K/AKT signaling pathway to promote cancer cell invasion and migration." (PMID 36077769, 2022). "This highlights MACC1 as a potential CCG, expanding the repertoire of CCGs involved in several hallmarks of cancer, including the cell cycle, proliferation and invasion, similar to MYC and RAS." (PMID 35884519, 2022). "With the observed role of MACC1 in the balance of TfR recycling and degradation, we analyzed its impact on CME-regulated internalization, recycling or degradation of other cancer-related signaling receptors." (PMID 33469705, 2021). "MACC1 has been shown to modulate the HGF/MET Akt/β-catenin and MAPK/PI3K/Akt signaling pathways in various cancers." (PMID 33854976, 2021). "As previous studies reported, the biological functions of MACC1 and SPINT1 can be observed in variety of cancers." (PMID 33751856, 2021). "In recent years, many literatures have reported on the abnormally high expression of MACC1 and SPON2 in various cancers and their potential applications in the development, progression and prognosis of cancer." (PMID 33712897, 2021). "In this study, real-time polymerase chain reaction was applied to analyze five SNPs of MACC1 rs1990172, rs975263, rs3095007, rs4721888, and rs3735615 in 378 patients with HCC and 1199 cancer-free controls." (PMID 32047570, 2020). "Our results demonstrated distinct prognostic roles of MACC1 mRNA expression in EOC patients and the difference in expression between cancer and normal tissue." (PMID 30515418, 2018). "In other cancer cells, many genes have been identified as miR-338-3p targets, including ADAM17, PREX2a, ZEB2, Sox4, SMO, MACC1, and IRS2." (PMID 29618948, 2018). "MACC1 controls hepatocyte growth factor (HGF)/Met signaling pathway and enhances migration, invasion, and metastasis of cancer cells." (PMID 30515418, 2018). "As a transcriptional activator, MACC1 directly regulates the transcription of numerous genes involved in EMT, metastasis, cancer stemness, and drug resistance, including MET, SPON2, and MDR1/ABCB115–18." (PMID 30082743, 2018). "MACC1 was previously reported to mediate invasion and metastasis by regulating HGF/c-Met signaling pathway in several cancer types." (PMID 28624808, 2017). "Surprisingly, the GEFs fared better as prognostic markers than two established markers of cancer progression, S100A4 and MACC1." (PMID 26916336, 2016). "The involvement of MACC1 and KAI1 in the recurrence and metastasis of GAC suggests that they should be valuable biomarkers for measuring cancer progression and developing higher accurately therapeutic targets." (PMID 27793161, 2016). "Importantly, MACC1 has also been identified as a valuable biomarker in carcinomas of the gastrointestinal tract such as gastric, esophagus, pancreatic and hepatobiliary as well as in carcinomas of the lung, ovaries, breast, upper urothelial tract, nasopharynx, malignant glioma and osteosarcomas." (PMID 25884643, 2015). "MACC1 acts as a master regulator of HGF-MET signaling pathway, whose activation has been found to play a critical role in oncogenesis and cancer metastasis." (PMID 22251819, 2012). "Third, the level of MACC1 was positively correlated with that of c-MET, which plays critical roles in cancer cell migration and metastasis." (PMID 21955323, 2011).
cancer (continued). "Thus, interventional approaches targeting MACC1 would potentially improve further targeted therapies for CRC patients to eradicate CSCs and prevent cancer recurrence and distant metastasis formation." (PMID 38339354, 2024). "MACC1 is a regulator of the HGF/c-Met, phosphatidylinositol 3-kinase (PI3K)/Akt and MAPK signalling pathways, which are known to play a crucial role in the growth of cancer cells." (PMID 39544485, 2024). "Similarly, RNA sequencing performed on PDO and PDX models demonstrated significantly increased MACC1 expression in ALDH1(+) CSCs, highlighting its involvement in cancer stemness." (PMID 38339354, 2024). "Clinical application of combined intervention strategies targeting MACC1 expression and GIPC1 expression might contribute to restrict MACC1-induced cancer metastasis and thus to improved patient survival." (PMID 38144523, 2023). "The levels of MACC1 expression, however, did not correlate with survival parameters in patients with other types of cancer." (PMID 36545127, 2022). "Our observation, that MACC1 and S100A4 form a signaling axis through β-catenin might add to characterization of molecular cancer subtypes with high metastatic potential and novel intervention points for improved anti-metastatic therapy." (PMID 36008464, 2022). "Our study concluded that MACC1 might be a novel regulator of CC by regulating the AKT/STAT3 pathway to change the migration, invasion, apoptosis, and cancer stemness of CC cells." (PMID 34939526, 2022). "Here we report on a novel MACC1-β-catenin-S100A4 axis and demonstrate that, based on this rationale, combined transcriptional inhibition of MACC1 and S100A4 restricts cancer cell motility and metastasis in CRC with seminal cross entity potential for cancer therapy." (PMID 36008464, 2022). "A differential MACC1 expression in HCT116 cells upon C. cardunculus treatment, as seen in WT and PER2-KO conditions, points towards the effect of C. cardunculus on clock and metastasis-related components with likely effects on cancer progression." (PMID 36012399, 2022). "Our results showed that MACC1 protein was abundant in PC tissues and was highly expressed in both paired and unpaired cancer tissues when compared to noncancerous tissues." (PMID 36333284, 2022). "In addition, MACC1 manipulation and CC knockout altered cell invasion properties of HCT116 cells, pointing to a regulation of clock and cancer progression in CRC, possibly via the interaction of MACC1 with core-clock genes." (PMID 35884519, 2022). "Hence, we provide evidence of a reciprocal interplay between MACC1 and circadian clock using our in vitro cellular model of CRC, with an impact on CRC progression, in particular cancer cell proliferation and invasion." (PMID 35884519, 2022). "Among the several related genes, we focused on metastasis-associated in colon cancer 1 (MACC1), known to be a driver for cancer metastasis, especially in CRC, and for which no connection to the circadian clock has been established to our knowledge." (PMID 35884519, 2022). "Consequently, we simultaneously targeted inducer MACC1 and enforcer S100A4 within this axis of metastasis by combining clinically established drugs and generated efficient restriction of cancer cell motility and metastasis formation." (PMID 36008464, 2022). "We used bioinformatics analysis to identify MET Transcriptional Regulator (MACC1) and Serine Peptidase Inhibitor Kunitz Type 1 (SPINT1) as candidate TFs with the respective downstream regulatory proteins for patient prognosis in pan‐cancer." (PMID 33751856, 2021). "It will be interesting to elucidate whether other cancer cell entities share IGFBP2 and MACC1 as pro-tumorigenic mediators for a common and synergistic consideration in future studies." (PMID 34830078, 2021).
cancer (continued). "We focused on MACC1 and SPINT1, which were identified as important molecules for further investigation of their transcriptional regulatory relationship, biological functions in GC cells, and pan‐cancer prognostic value." (PMID 33751856, 2021). "In the current study, we selected five MACC1 SNPs rs1990172, rs975263 (exon 5), rs3095007, rs4721888 (exon 4), rs3725615 (exon 7), and try to elucidate their correlations to Taiwanese HCC patients and cancer prognosis." (PMID 32047570, 2020). "Since MACC1 is a positive regulator of c-MET, a receptor for hepatocyte growth factor, circ-PDE8A activates downstream signaling factors, such as Akt and ERK1/2, thereby promoting invasive growth and metastasis of cancer cells." (PMID 32756339, 2020). "In addition, it is known that depletion of MACC1 also leads to disruption of the HGF/c-Met signaling pathway and sensitizes chemotherapy-resistant cancer cells." (PMID 33425885, 2020). "Despite the unexpected findings of invasion assay, we assessed by RT-qPCR that some FOXM1 downstream targets involved in metastasis, cancer progression, and cisplatin resistance, such as MMP2 and MACC1, were specifically down-regulated in OSPC2 cells after FOXM1 silencing." (PMID 28482906, 2017). "Meanwhile, MACC1 could be bound to the promoter of the MET gene and activate the HGF/MET signaling pathway to promote cancer cell proliferation, invasion, and metastasis." (PMID 27793161, 2016). "Although multiple studies demonstrate that MACC1 overexpression is correlated with worse clinical outcomes in cancer patients, no systematic evidence has been provided to verify the prognostic value of MACC1 in digestive system neoplasms." (PMID 26090393, 2015). "MACC1 protein was overexpressed in all six examined primary HCC samples, displaying more than 2-fold increase of MACC1 expression as compared that in the adjacent non-cancer tissue samples." (PMID 23717574, 2013). "Combining MACC1 with circulating transcripts of the metastasis gene S100A4, a transcriptional target of the Wnt/β-catenin-pathway, improves survival prediction for newly diagnosed cancer patients." (PMID 23166620, 2012). "Our study shows that MACC1 was expressed highly in HCC samples and cultured cancer cell lines." (PMID 21955323, 2011). "MACC1 expression levels were significantly correlated with immune invasion (B cells, CD4+ T cells, CD8+ T cells, neutrophils, macrophages, and dendritic cells) and most immune markers in more than two dozen cancers studied, but the nature of this correlation varied between cancer types." (PMID 36979146, 2023). "Additionally, we observed a negative correlation between MACC1 and two cancer and clock modulators, namely HRAS and SIRT1, known to affect the period of oscillation." (PMID 35884519, 2022). "Furthermore, we have established the predictive signature model combining MACC1 with SPINT1 for prognosis prediction in patients with GC and other seven cancer types, which will lay a foundation for the development of new biomarkers and targeted therapies in multiple cancer types." (PMID 33751856, 2021). "However, the exact role of MACC1 SNPs in Taiwanese HCC patients to cancer progression and development remained not well-investigated." (PMID 32047570, 2020). "Although MACC1 and S100A4 are involved in different biological pathways, that is, MACC1 as a key regulator of HGF‐MET signaling and S100A4 as a transcriptional target of β‐catenin/T‐cell factor signaling, our data suggest that MACC1 and S100A4 might be co‐regulated in cancer." (PMID 30927479, 2019).
benign tumor (2 papers, 2016 to 2021). "Compared with the healthy control and benign tumor groups, serum MACC1 were elevated in BC patients at any TNM stage (I, II or III)." (PMID 27793048, 2016).
digestive system neoplasm (1 paper, 2015). A neoplasm (disease) that involves the digestive system. "As a novel oncogene, MACC1 overexpression has been associated with poor clinical outcome of patients with digestive system neoplasms." (PMID 26090393, 2015). "Yet large multicenter random control trials should be conducted in the future as to verify the prognostic value of MACC1 in digestive system neoplasms." (PMID 26090393, 2015). "Here we synthesize the existing literature to evaluate the prognostic value of MACC1 in digestive system neoplasms." (PMID 26090393, 2015). "Yet the results of both studies support the systematic evidence yielded from this meta-analysis which is that high MACC1 expression leads to poorer clinical outcomes in patients with digestive system neoplasms." (PMID 26090393, 2015). "Pooled HRs indicated that high MACC1 expression significantly correlates with poorer OS in patients with digestive system neoplasms (HR = 1.94; 95% CI: 1.49–2.53) as well as poorer relapse-free survival (HR = 1.94, 95% CI: 1.33–2.82)." (PMID 26090393, 2015). "As a whole, our meta-analysis provides relatively comprehensive evidence on the role of MACC1 expression level in prognostic value in patients with digestive system neoplasms." (PMID 26090393, 2015). "Therefore, we examined the correlation between high levels of MACC1 and OS in patients with digestive system neoplasm extracted from 18 eligible studies via systematic review and meta-analysis." (PMID 26090393, 2015). "However, the prognostic value of MACC1 in digestive system neoplasms needs systematic evidence to verify." (PMID 26090393, 2015). "To conclude, the evidence provided by this systematic review and meta-analysis suggests that MACC1 might be served as a prognostic biomarker for digestive system neoplasms." (PMID 26090393, 2015). "In conclusion, high MACC1 expression may serve as a prognostic biomarker to guide individualized management in clinical practice for digestive system neoplasms." (PMID 26090393, 2015). "The results suggested that high MACC1 expression is significantly correlated with both poorer OS and poorer RFS in patients with digestive system neoplasms." (PMID 26090393, 2015). "Whether high MACC1 expression is correlated with poorer clinical outcomes needs further proof and the prognostic value of MACC1 in digestive system neoplasms has not been validated by systematic review and meta-analysis." (PMID 26090393, 2015).
infection (1 paper, 2022). The state of being infected such as from the introduction of a foreign agent such as serum, vaccine, antigenic substance or organism. "We then stably overexpressed MACC1 in PANC-1 and SUIT-2 cells with low MACC1 levels via lentiviral infection, as verified by qRT–PCR and western blotting." (PMID 36333284, 2022).
MACC1 also shares sentences with these, for which no sentence is quoted: esophageal cancer (5 papers); adenocarcinoma (3); gynecological cancers (3); cancers of the gastrointestinal tract (2); metastatic colorectal cancer (2); Oral Squamous Cell Carcinoma (2); renal cell carcinoma (2); retinoblastoma (2); acromegaly (1); acute lymphoblastic leukemia (1); acute myeloid leukemia (1); cervical (1); colitis (1); diffuse large B-cell lymphoma (1); dysplasia (1); endocervical adenocarcinoma (1); esophageal adenocarcinoma (1); gastric cardia adenocarcinoma (1); Hypertension (1); Klatskin's tumor (1); lipoma (1); liver neoplasm (1); lymph node (1); neuroblastoma (1); ovarian serous cystadenocarcinoma (1); pancreatic adenocarcinoma (1); pancreatic ductal adenocarcinoma (1); paraganglioma (1); pheochromocytoma (1); pulmonary arterial hypertension (1).
A further 11 diseases each share a sentence with MACC1 in 1 paper.